RUNX2 (RUNX family transcription factor 2)
Diseases named in the same sentence as RUNX2 in open-access papers (continued):
Sharing a sentence is not in itself a finding about the gene and the disease.
osteosarcoma (continued). "Intriguingly, we showed herein that CBX4 could promote Runx2 transcription in osteosarcoma by recruiting GCN5 to sustain H3K27Ac at the Runx2 promoter, consequently facilitating osteosarcoma metastasis." (PMID 32111827, 2020). "Interestingly, gene knockdown of PPARδ or SCD-1 seemed to partially increases the endogenous Runx2 and OCN mRNA expressions in MG63 osteosarcoma cells." (PMID 32630668, 2020). "Interestingly, these authors identified that MYC is a direct target of RUNX2, and they also demonstrated that MYC is required for the survival of osteosarcoma cells." (PMID 30463392, 2018). "To determine whether WWOX regulates bcl-2, RUNX2, VEGF, and OPN expression in osteosarcoma cells, we used Western blotting and qRT-PCR to examine protein and mRNA levels of these factors in U2OS, SAOS2, and MG-63 cells with WWOX overexpression or knockdown." (PMID 28977834, 2017). "In addition, WWOX inhibited the expression of bcl-2, OPN, RUNX2, and VEGF in osteosarcoma cells, while bcl-2 increased VEGF expression and RUNX2 increased VEGF and OPN expression in MG-63 cells." (PMID 28977834, 2017). "To characterize the regulatory cascade involving WWOX, bcl-2, OPN, RUNX2, and VEGF in osteosarcoma cells, we transfected MG-63 cells overexpressing WWOX with bcl-2 or RUNX2 expression plasmids and measured WWOX, bcl-2, OPN, RUNX2, and VEGF expression using Western blotting." (PMID 28977834, 2017). "Second, osteosarcoma frequently exhibits expression of early osteogenic differentiation markers such as RUNX2 and OSX1 but not terminal differentiation markers, osteocalcin and osteopontin." (PMID 23533324, 2013). "Accordingly, RUNX2 was significantly higher expressed in our osteosarcoma clinical samples, relative to normal bone (results not shown) as has been shown for the comparison of osteosarcoma tumors with osteoblasts." (PMID 23133552, 2012). "In pituitary tumours, RUNX2 upregulates the anoikis suppressor galectin-3 (LGALS3), which may also facilitate osteosarcoma metastasis." (PMID 21197465, 2011). "RUNX1 and RUNX2 upregulate LGALS3 (galectin-3), a protein which suppresses anoikis and drug-induced apoptosis and whose expression is correlated with metastasis in osteosarcoma and progression in glioma." (PMID 20465837, 2010). "Therefore, we recommend that regulating RUNX2 and HIF-1α and addressing their molecular interactions is a crucial therapeutic target for osteosarcoma, which could enhance overall and disease-free survival." (PMID 40806771, 2025). "Thus, there may be an intricate relationship between RUNX2 and HIF-1α that allows them to complete each other or may work synergistically to develop resistance to therapy and promote osteosarcoma progression." (PMID 40806771, 2025). "Therefore, regulation of these two major factors, RUNX2 and HIF-1α, may help overcome chemotherapeutic resistance, enhance overall and disease-free survival in patients with osteosarcoma, and stand out as an effective therapeutic approach." (PMID 40806771, 2025).
osteosarcoma (continued). "Hence, our review focused on highlighting the intricate network between RUNX2 and HIF-1α, which support each other or may work synergistically to develop resistance to therapy and osteosarcoma progression." (PMID 40806771, 2025). "In addition, the canonical Wnt pathway can also activate the transcription factor RUNX2 in promoting osteogenesis and in osteosarcoma, while the non-canonical route activates JNK." (PMID 39456171, 2024). "The expression of early osteogenic differentiation marker genes (i.e., ALPL, RUNX-2, and COL1A1) and the ALP enzymatic activity, whose functionally mirrors the differentiation grades of osteoblastic cells, have been reported to be involved in metastasis in osteosarcoma patients." (PMID 37175397, 2023). "The nitric oxide (NO) treatment of the MG-63 osteosarcoma cell line was shown to enhance RUNX2-mediated BCL2 expression, which improves cell viability under oxidative stress, in contrast to results that suggested that RUNX2 upregulates BAX expression in the SAOS-2 cell line." (PMID 37370857, 2023). "An inverse WWOX and RUNX2 interaction was not as clear in human osteosarcomas as in cell lines." (PMID 36271927, 2022). "In addition, depletion of other CBX family members, such as CBX2 and CBX6, or PRC1 core subunits, Ring1a and Ring1b, did not consistently show to affect the mRNA level of Runx2 in these osteosarcoma cell lines." (PMID 32111827, 2020). "Adding RANKL to cultures of RANK-expressing osteosarcoma seems to boost osteosarcoma cell pseudo-differentiation to a more mature stage with respectively increased and decreased expressions of late and early osteoblast differentiation markers such as BSP and RUNX2." (PMID 30355966, 2018). "Hence, preferential expression of RUNX2 from the ‘early-activated’ P2 promoter rather than the ‘late-activated’ P1 promoter in osteosarcomas suggests that osteosarcomas may originate from immature mesenchymal progenitor cells." (PMID 24835790, 2014). "The function of RUNX2 in osteosarcoma has not yet been identified, but given the complex functionality of RUNX2 in developing osteoblasts, deregulation of the protein could act during osteosarcoma pathogenesis." (PMID 21197465, 2011). "Our understanding of the role of RUNX2 in osteoblasts and osteosarcoma cells where the gene is endogenously expressed, provides a biological framework for analyzing the regulation and regulatory roles of RUNX2 in non-osseous cancer cells (for example, breast) in which RUNX2 is ectopically expressed." (PMID 21029421, 2010). "WWOX overexpression decreased, while WWOX knockdown increased, RUNX2, bcl-2, VEGF, and OPN protein and mRNA levels in osteosarcoma cells compared to the normal and negative controls." (PMID 28977834, 2017).
cleidocranial dysplasia (143 papers, 2005 to 2026). "A deep-intronic single nucleotide variant in RUNX2 causes the characteristic clinical features of cleidocranial dysplasia (CCD) in a family via pseudo-exon inclusion into the mRNA." (PMID 41797213, 2026). "In humans, RUNX2 haploinsufficiency causes cleidocranial dysplasia associated with deficient midfacial growth." (PMID 40442075, 2025). "This congenital disorder, also known as Marie-Sainton disease or cleidocranial dysostosis, arises from mutations in the Runt-related transcription factor 2 (RUNX2 gene; previously known as core binding factor subunit alpha or CBFA1) located on chromosome 6p21." (PMID 40895890, 2025). "The loss of the positively charged arginine residue destabilizes the protein structure and disrupts its interaction with other transcription factors, confirming the diagnosis of cleidocranial dysplasia (CCD) secondary to a heterozygous RUNX2 mutation." (PMID 41030579, 2025). "Cleidocranial dysplasia (OMIM #119600) results from mutations in the RUNX family transcription factor 2 (RUNX2) gene on chromosome 6p21, a transcription factor critical for osteoblast differentiation and bone formation." (PMID 40004475, 2025). "RUNX2 is the master regulator of osteoblast differentiation and is essential for skeletal development; mutations in RUNX2 are associated with cleidocranial dysplasia." (PMID 40990016, 2025). "Genetic testing confirmed a heterozygous pathogenic variant in the RUNX2 gene, consistent with a diagnosis of cleidocranial dysplasia." (PMID 41030579, 2025). "RUNX2 haploinsufficiency in humans and mice causes cleidocranial dysplasia associated with midface hypoplasia related to reduced anterior-posterior skull growth and open posterior frontal and sagittal cranial sutures." (PMID 40442075, 2025). "Cleidocranial dysplasia is caused by a heterozygous loss-of-function mutation of the Runt-related transcription factor 2 gene (RUNX2; OMIM 600211)." (PMID 38534443, 2024). "Pathogenic genes in most patients with cleidocranial dysplasia have been confirmed to be runt-related transcription factor 2 (RUNX2), which controls mutations in specific osteoblast transcription factors and affects skull ossification and suture adhesion." (PMID 39584128, 2024). "Cleidocranial dysostosis is a rare autosomal dominant genetic disorder caused by RUNX2 gene mutations or induced de novo." (PMID 38929327, 2024). "Heterozygous mutations in RUNX2 cause cleidocranial dysplasia (CCD), which is characterized by hypoplastic clavicles, open fontanelles, supernumerary teeth, and short stature." (PMID 39337587, 2024). "DFSCs also play a key role in tooth eruption disorders caused by cleidocranial dysplasia, where DFSCs can regulate osteoclast activity through the RUNX2-miR-31-SATB2 pathway, thus affecting the timing and extent of tooth eruption." (PMID 39834384, 2024). "Recently, a novel exonic microdeletion in the RUNX2 gene was found in a 5-year-old girl with clavicular hypoplasia, which has been shown to cause cleidocranial dysplasia [36•]." (PMID 36795294, 2023). "Cleidocranial dysplasia (CCD) is a genetic disorder caused by mutations in the RUNX2 gene, affecting bone and teeth development." (PMID 37500953, 2023). "Cleidocranial dysplasia (CCD) is a rare genetic defect caused by a heterozygous mutation of runt-related transcription factor 2 (RUNX2), which is important for osteoblast and skeletal development." (PMID 38068903, 2023). "Haploinsufficiency of RUNX2 causes cleidocranial dysplasia (CCD) syndrome, characterized by incomplete closure of the fontanelle, hypoplasia of the clavicle, short stature, and supernumerary teeth in both humans and mice." (PMID 37648716, 2023). "For example, we identified putative enhancers of BMPR1B and IHH (both genes are associated with brachydactyly type-A, OMIM #112500), and candidate enhancers of RUNX2, a gene linked to cleidocranial dysplasia, with brachydactyly (OMIM #119600)." (PMID 35896673, 2022).
cleidocranial dysplasia (continued). "RUNX2 plays a central role in osteogenesis; Runx2 mutations cause cleidocranial dysplasia, a skeletal disorder." (PMID 35652047, 2022). "The master regulator of bone formation is the transcription factor Runx2, and haploinsufficiency of Runx2 causes the hereditary bone disease cleidocranial dysplasia." (PMID 34981783, 2022). "In humans, RUNX2 haploinsufficiency causes cleidocranial dysplasia (CCD), associated with hypoplastic clavicles, patent sutures and fontanelles, supernumerary teeth and short stature." (PMID 35887171, 2022). "A hard and soft palate has also been observed in cleidocranial dysplasia, which is a rare congenital skeletal dysplasia caused by haploinsufficiency in the RUNX2 gene." (PMID 35455561, 2022). "Mutation of Runx2 is related to skeletal malformation syndromes, including cleidocranial dysplasia (CCD)." (PMID 36217388, 2022). "Mutation of Runx2 causing cleidocranial dysplasia negatively affects osteogenesis and the osteoclastic ability of dental follicles, resulting in tooth eruption difficulties." (PMID 36175952, 2022). "Heterozygous mutations of the Runx2 gene cause an autosomal dominant human disease termed cleidocranial dysplasia (CCD; OMIM119600)." (PMID 35883659, 2022). "Mutation of Runx2 causing cleidocranial dysplasia (CCD) negatively affects osteogenesis and the osteoclastic ability of dental follicles, resulting in tooth eruption difficulties." (PMID 36175952, 2022). "iPSCs have also been generated from DPCs of patients with cleidocranial dysplasia, which is a genetic disease characterized by a loss of function of Runt-related transcription factor 2 (RUNX2)." (PMID 34203719, 2021). "Cleidocranial dysplasia is a skeletal dysplasia caused by mutations in the bone/cartilage-specific osteoblast transcription factor RUNX2 gene." (PMID 33919113, 2021). "RUNX2 haploinsufficiency causes cleidocranial dysplasia (CCD), a developmental disorder characterized by an altered growth of membranous bones, including hypoplasia or aplasia of the clavicles, delayed closure of cranial sutures and dental anomalies." (PMID 34716352, 2021). "Cleidocranial dysplasia (CCD) is mainly attributable to a variant of runt-related transcription factor 2 (RUNX2) on chromosome 6p21." (PMID 34766588, 2021). "Pathogenetic variants in the RUNX2 gene are generally associated with cleidocranial dysplasia with autosomal dominant inheritance (cleidocranial dysplasia, CCD, OMIM # 119600)." (PMID 34946295, 2021). "In a cleidocranial dysostosis model, the mutation in RUNX2 gene was repaired in iPSCs derived from mucosal tissues of affected patients." (PMID 32300365, 2020). "Mutations on one allele of human Runx2 gene cause cleidocranial dysplasia, while deletion of Runx2 in mice leads to a complete failure of bone formation and ossification." (PMID 32012654, 2020). "Skull radiography of patients with cleidocranial dysplasia caused by RUNX2 haploinsufficiency showed persistent synchondroses primarily associated with defective development of membranous bones." (PMID 32850826, 2020). "In this context, repairing RUNX2 gene mutation in iPSCs derived from cleidocranial dysostosis patients as well as transducing nuclear matrix protein SATB2 and Alox5 gene into iPSCs promoted osteodifferentiation." (PMID 32300365, 2020). "Haploinsufficiency in RUNX2 causes cleidocranial dysplasia (CCD), which is characterized by open fontanelle and hypoplastic clavicles." (PMID 32788656, 2020). "Pathogenic variants in RUNX2 have been implicated in skeletal disorders such as cleidocranial dysplasia, dental anomalies, and brachydactyly." (PMID 31288860, 2019). "Mutations in Runx2 are responsible for inherited cleidocranial dysplasia (CCD), an autosomal-dominant disorder characterized by elevated supernumerary tooth formation." (PMID 29581460, 2018).
cleidocranial dysplasia (continued). "Cleidocranial dysplasia (CCD) is a rare hereditary disorder that arises from heterozygous loss of function mutations in the runt-related transcription factor 2 (RUNX2) gene." (PMID 28056872, 2017). "Tooth development arrests at the bud stage in Runx2-deficient mice, while heterozygous mutations in RUNX2 cause the human disorder cleidocranial dysplasia (CCD), which is characterized by multiple supernumerary teeth." (PMID 27518316, 2016). "It appears that adequate RUNX2 is also dosage-dependent since haploinsufficiency of Runx2 in mice or RUNX2 in humans causes hypoplastic clavicles and delayed closure of the fontanelles, defects that are characteristic of cleidocranial dysplasia in humans." (PMID 27298623, 2016). "RUNX2 deficient mice died shortly after birth with skeletal abnormalities of cleidocranial dysplasia (CCD)." (PMID 27007162, 2016). "Rare mutations in RUNX2 cause Cleidocranial dysplasia, an autosomal dominant disorder involving alterations of cranial ossification (OMIM #119600)." (PMID 27193062, 2016). "Cleidocranial dysplasia, an autosomal dominant condition caused by mutations of RUNX2, likewise results in insufficient dentin and enamel mineralization and other dental anomalies." (PMID 28111553, 2016). "Second, the osteocalcin promoter contains a cis-acting element termed ose2, a binding site for the osteoblast transcriptional regulator Runx2, which has been implicated in cleidocranial dysplasia in humans and mice." (PMID 27483347, 2016). "Nonsense and missense mutations in RUNX2 have also been observed in several Chinese patients with cleidocranial dysplasia." (PMID 26719974, 2015). "Loss of function of the α-subunit of Runx2 due to mutation, if the identical β-subunit is preserved (Runx2+/−), results in the formation of cleidocranial dysplasia (dysostosis), whereas the Runx2−/− genotype is nonsurvivable." (PMID 26649300, 2015). "The loss-of-function of RUNX2, associated with polyA-expansion or with other mutations, is a fundamental pathogenetic mechanism of cleidocranial dysplasia." (PMID 24497578, 2014). "Mutation of Runx2 causes cleidocranial dysplasia; patients with this condition, many of whom have an inherited heterozygotic mutation in the coding region of the gene, exhibit defective endochondral and intramembranous ossification." (PMID 25244033, 2014). "Dental abnormalities can be found in the human syndrome cleidocranial dysplasia, which occurs due to haploinsufficiency caused by Runx2 mutations." (PMID 25369078, 2014). "Cleidocranial dysplasia, which is induced by mutations in RUNX2, was found to be the result of a haploinsufficient mutation on RUNX2." (PMID 23979934, 2013). "Mutations of RUNX2 in humans induce incomplete development of osteoblasts, which results in cleidocranial dysplasia and osteosarcoma." (PMID 23979934, 2013). "Heterozygous mutations in coding and promoter regions of RUNX2 in humans cause the skeletal syndrome Cleidocranial Dysplasia (CCD)." (PMID 24086263, 2013). "Mutations in Runx2/Cbfa1 are associated with Cleidocranial dysplasia, which causes underdevelopment of bones and joints and multiple unerupted supernumerary teeth." (PMID 23533592, 2013). "The reduction of the amount of Runx2 mRNA causes developmental defects in calvarial bones, called cleidocranial dysplasia, in mouse embryos." (PMID 24711977, 2013). "It has been suggested that 70% of patients with cleidocranial dysplasia have a point mutation involving Runx2 and 13% have a deletion." (PMID 22260259, 2012). "Heterozygous mutations in coding and promoter sequences of RUNX2 cause the dominantly inherited skeletal syndrome cleidocranial dysplasia (CCD)." (PMID 22912713, 2012). "Cleidocranial dysplasia is a rare congenital defect of autosomal dominant inheritance caused by mutations in the Cbfa1 gene, also called Runx2, located on the short arm of chromosome 6." (PMID 22260259, 2012).